FZD10 (frizzled class receptor 10)
Diseases named in the same sentence as FZD10 in open-access papers (continued):
Sharing a sentence is not in itself a finding about the gene and the disease.
tumor (continued). "Tumor growth could be attenuated by targeting FZD10 through small-interfering RNA or humanized antibodies or by inducing epigenetic silence of FZD10." (PMID 27391060, 2016). "This suggests that exosomal FZD10 protein and FZD10-mRNA may induce tumour growth and metastasis." (PMID 33669294, 2021). "Tumor migration and invasive behavior are facilitated by several CCA-derived EVs, such as EV-integrin-a or -b, EV-frizzled class receptor 10 (FZD10), EV-vitronectin, and EV-lactadherin, which alter several signaling pathways in the recipient cells." (PMID 40650114, 2025). "FZD1/2/3/4/5/7/8 expression was significantly higher in tumor tissues than in normal brain tissues; however, FZD9 and FZD10 expression was higher in normal tissues." (PMID 36699699, 2022). "STXBP6 protein expression was downregulated in 91.43% of tumor tissues, BCL6B was downregulated in 88.57%, FZD10 was downregulated in 88.57%, and HSPB6 was downregulated in 91.43% (p <0.001, the original blots of western blots is shown in the S1–S8 Figs)." (PMID 30286088, 2018). "STXBP6 mRNA expression was downregulated in 66.67% of tumor tissues, BCL6B was downregulated in 69.23%, FZD10 was downregulated in 71.79%, and HSPB6 was downregulated in 74.36% (p <0.001)." (PMID 30286088, 2018). "The possible occurrence of an actual relationship in tissues between FZD10 or ERK/p-ERK1/2 and the clinicopathological factor Ki-67 is a key issue that needs to be closely assessed to understand the role of these tumor-activated proteins in CRC and GC patients." (PMID 34671555, 2021). "Moreover, LEF treatment significantly inhibits the FZD10 (receptor mediating WNT/β-catenin activation) expression level and elsewhere, vivo xenograft experiment demonstrated inhibitory effects of LEF on tumor growth and Wnt/β-catenin signaling." (PMID 33758612, 2021). "FZD10 mRNA is increased in FLC tumor relative to the adjacent normal tissue by Δlog2 = 6.13 with padj = 3.08 × 10−20 and the FZD10 protein is also increased in the FLC tumor." (PMID 29535801, 2018). "In vivo, when radiolabelled with Indium-111 (111In), it bound and accumulated in up to 5 days after IV injection in SS tumor cells overexpressing FZD10 (SYO-1) implanted in nude mice and not in FZD10 negative SS tumor cells (LoVo)." (PMID 29884132, 2018). "Blocking experiments with non-labeled 1 as well as the low accumulation observed in a FZD10 negative SS tumor model confirmed specific tumor accumulation." (PMID 30583594, 2018). "The in vivo expression of FZD10 was not assessed on tumor biopsy as this procedure is exposed to sampling error and may not reflect the entire tumor cells heterogeneity." (PMID 29884132, 2018). "When it was radiolabeled with Yttrium-90 (90Y), a highly energetic beta emitter radioisotope, tumor shrinkage was observed in immunocompromised Balb-c mice bearing established FZD10-positive SS tumor subcutaneous xenografts (SYO-1 cell line), without significant toxicity." (PMID 29884132, 2018). "Astatine-211-OTSA101, an α-emitting anti-FZD10 RIC, suppressed tumor growth of SS mouse xenografts more efficiently than the same dose of the Yttrium-90-OTSA101, a β-emitting anti FZD10 RIC, without remarkable toxic side effects." (PMID 34440182, 2021). "The analysis of the corresponding tumor and non-tumor samples also revealed upregulation of COMP, matrix proteins such as COL5A1, COL11A1, and FN1, and genes of the Wnt pathway (WNT7B, FZD10, SFRP2), while PLCB1, CAMK2B, PLCB4 and WIF1 are downregulated." (PMID 33227073, 2020).
tumor (continued). "The methylation and expression validation results identified 4 candidate genes (STXBP6, BCL6B, FZD10, and HSPB6) that were significantly hypermethylated and downregulated in most of the tumor tissues compared with the noncancerous lung tissues." (PMID 30286088, 2018).
FZD10 also shares sentences with these, for which no sentence is quoted: nasopharyngeal carcinoma (3 papers); ovarian cancer (3); sarcoma (3); glioma (2); lymph node metastasis (2); pancreatic carcinoma (2); adenoma (1); colonic polyps (1); colorectal (1); colorectal adenoma (1); glioblastoma (1); granulosa cell tumor (1); head and neck squamous cell carcinoma (1); infection (1); kidney disease (1); medulloblastoma (1); mucoepidermoid carcinoma (1); pancreatic adenocarcinoma (1); panic disorder (1).